TUG1 (taurine up-regulated 1)
Diseases named in the same sentence as TUG1 in open-access papers (continued):
Sharing a sentence is not in itself a finding about the gene and the disease.
lupus nephritis (4 papers, 2020 to 2025). Glomerulonephritis in the context of systemic lupus erythematosus. "Overall, our findings illustrated for the first time that TUG1 gene rs5749201 and rs886471 variants were associated with increased risk of SLE, more severe disease, and lupus nephritis, and the TUG1 level could be used as a diagnostic biomarker of SLE and lupus nephritis." (PMID 37736902, 2023). "Urinary TUG1 level was significantly lower in class V lupus nephritis compared to primary membranous nephropathy or minimal change nephropathy." (PMID 37511572, 2023). "With ROC curve analysis, the AUC of TUG1 for the identification of class V lupus nephritis was 0.795 (p = 0.004)." (PMID 37511572, 2023). "In the third study, urinary levels of lncRNA TUG1 were compared between 36 patients with pure class V lupus nephritis, primary membranous nephropathy, or minimal change nephropathy." (PMID 37511572, 2023). "Previous studies showed that TUG1 contributed to the protection of NF-κB inhibition after kidney injury in murine models of SLE, and TUG1 alleviated LPS-induced mesangial cell injury through regulation of the miR-153-3p/Bcl-2 axis in lupus nephritis." (PMID 37511572, 2023). "Therefore, we aimed in this study to investigate for the first time the role of TUG1 gene polymorphism and the TUG1 level as biomarkers in systemic lupus erythematosus (SLE) and their link to lupus nephritis 145 SLE." (PMID 37736902, 2023). "Urinary taurine-upregulated gene 1 (TUG1) level was significantly lower in pure class V lupus nephritis than primary membranous nephropathy (p = 0.003) and minimal change nephropathy (p = 0.04), and urinary TUG1 level correlated with eGFR in class V lupus nephritis (r = 0.706, p = 0.01)." (PMID 37511572, 2023). "Moreover, urinary TUG1 level significantly correlated with eGFR in patients with pure class V lupus nephritis (r = 0.706, p = 0.01) and those with primary membranous nephropathy (r = 0.771, p = 0.001), though it did not correlate with minimal change nephropathy." (PMID 37511572, 2023). "TUG1 expression was significantly higher in SLE than in the control and in the lupus nephritis than in non-lupus nephritis cases (p < 0.05)." (PMID 37736902, 2023). "Interestingly, the levels of the lncRNA TUG1 were significantly lower in the SLE patients, which was more evident in SLE patients affected by lupus nephritis." (PMID 32674342, 2020).
papillary thyroid cancer (4 papers, 2019 to 2023). "By analysing the expression of E-cadherin and N-cadherin, Lei confirmed that LncRNA TUG1 affects EMT in papillary thyroid carcinoma." (PMID 31585531, 2019). "LncRNA TUG1 facilitates the development of papillary thyroid cancer via miR-145/ZEB1 axis." (PMID 32795273, 2020).
Parkinson disease (4 papers, 2015 to 2025). A progressive degenerative disorder of the central nervous system characterized by loss of dopamine producing neurons in the substantia nigra and the presence of Lewy bodies in the substantia nigra and locus coeruleus. "In Parkinson’s disease, silencing TUG1 can inhibit SH-SY5Y cell apoptosis and reduce neuroinflammation, thus playing an effective protective role." (PMID 34787069, 2021). "In addition, studies have confirmed that TUG1 is overexpressed in Parkinson’s disease." (PMID 34787069, 2021). "In addition, TUG1 downregulation reduces oxidative stress, apoptosis, neuroinflammation, and pathological damage in SH-SY5Y cells of Parkinson's model by the miR-152-3p and PTEN under-expressions." (PMID 37620425, 2023).
preeclampsia (4 papers, 2022 to 2024). Preeclampsia is a hypertensive disorder of pregnancy that is characterized by new-onset hypertension with proteinuria presenting after 20 weeks of gestation, and depending on mild or severe forms may initially present with severe headache, visual disturbances, and hyperreflexia. "TUG1 affected trophoblasts’ biological function, including cell growth, migration, and crosstalk in vitro, and promoted the progression of preeclampsia." (PMID 38666946, 2024). "The lncRNA TUG1 was downregulated in the placental tissue of Preeclampsia patients compared to healthy pregnant women, and this downregulation decreased cell proliferation, migration, and invasion while promoting trophoblast death." (PMID 37745705, 2023). "TUG1 induction is multifunctional regarding proliferation, invasion, and angiogenesis promotion of trophoblasts in the setting of preeclampsia." (PMID 36163177, 2022). "While TUG1 downregulation boosted the expression of the enhancer of zeste homolog 2 (EZH2) and decreased the levels of the Rho family GTPase 3 (RND3) in Preeclampsia, it prevented remodeling of the uterine spiral artery." (PMID 37745705, 2023).
systemic lupus erythematosus (4 papers, 2022 to 2024). An autoimmune multi-organ disease typically associated with vasculopathy and autoantibody production. "TUG1 expression was also found to be markedly lower in PBMCs from systemic lupus erythematosus patients and to be further decreased in SLE patients with LN, with the lower expression in monocytes than in either T or B cells." (PMID 35796900, 2022). "For example, lncRNAs, such as Hotair, LUST, anti-NOS2A, MEG9, SNHG4, TUG1, and NEAT1, have been found to be highly expressed in rheumatoid arthritis, while the expression of lnc-HSFY2–3:3 and lnc-SERPINB9–1:2 is reduced in systemic lupus erythematosus (SLE)." (PMID 38473997, 2024). "Urinary TUG1 level did not correlate with the severity of proteinuria or the degree of tubulointerstitial scarring in the morphometric study, and this level in the lupus group also did not correlate with SLEDAI score or histological activity or chronicity indices." (PMID 37511572, 2023).
temporal lobe epilepsy (4 papers, 2021 to 2025). A localization-related (focal) form of epilepsy characterized by recurrent seizures that arise from foci within the temporal lobe, most commonly from its mesial aspect. "It was reported that lncRNA TUG1 can regulate hippocampal neuron cell activity and apoptosis which may be a biomarker of temporal lobe epilepsy diagnosis in children." (PMID 35603469, 2022). "The diagnostic capability of the elevated levels of TUG1 measured in children with temporal lobe epilepsy (TLE) has been further explored, revealing that TUG1 shows high sensitivity and specificity in children with TLE, strongly suggesting the diagnostic potential of TUG1 in children with TLE." (PMID 35290166, 2022).
Alzheimer disease (3 papers, 2021 to 2022). A progressive, neurodegenerative disease characterized by loss of function and death of nerve cells in several areas of the brain leading to loss of cognitive function such as memory and language. "Previous studies have suggested that lncRNA TUG1 participates in the development of cancers, hypoxic pulmonary hypertension, and Alzheimer’s disease." (PMID 34335559, 2021). "Interestingly, in a model of Alzheimer’s disease, TUG1 silencing can increase neuron cell survival and inhibit apoptosis of hippocampal neurons." (PMID 34787069, 2021).
ankylosing spondylitis (3 papers, 2020 to 2024). An autoimmune chronic inflammatory disorder characterized by inflammation in the vertebral joints of the spine and sacroiliac joints. "One study reported that serum levels of TUG1 were negatively correlated with CRP in ankylosing spondylitis patients." (PMID 39539543, 2024). "Another study discovered that lncRNA TUG1 is greatly lower in ankylosing spondylitis patients compared to controls and correlates with decreased disease activity, a short course of treatment, and a reduced rehospitalization rate." (PMID 32547537, 2020).
brain tumour (3 papers, 2016 to 2023). "TUG1-DDS was specifically accumulated and retained at least 24 h in brain tumours." (PMID 27922002, 2016).
clear cell renal cell carcinoma (3 papers, 2018 to 2022). "Lv noted that the long non-coding RNA TUG1 promotes cell proliferation through the MIR-31-5p/FLOT1 axis in clear cell renal cell carcinoma and inhibits apoptosis and autophagy." (PMID 35910212, 2022). "For example, the TUG1 level in clear cell renal cell carcinoma (ccRCC) tissues was significantly higher than that in adjacent nontumour tissues." (PMID 30595764, 2018).
diabetic retinopathy (3 papers, 2022 to 2023). "The influence of TUG1 on mitochondrial bioenergetics is further emphasized in the context of diabetic retinopathy." (PMID 36173935, 2022). "Taurine upregulated gene 1 (TUG1), a well-studied lncRNA in many types of cancer, was previously associated with diabetic retinopathy in mice being an aging-induced disease." (PMID 36173935, 2022). "In addition, TUG1 is involved in diabetic retinopathy in mice and many types of cancer via a nuclear or cytoplasmic function." (PMID 36173935, 2022).
hepatitis B (3 papers, 2017 to 2022). "AFP mRNA levels showed strong positive correlations with TUG1 and unfavorable prognosis in patients with non-hepatitis B/non-hepatitis C HCC (NBNC-HCC)." (PMID 31973032, 2020). "Lin and co-workers found that T3/TR treatment reduced TUG1 expression in vitro, resulting in the downregulation of alfa fetoprotein (AFP) mRNA in patients with non-hepatitis B/non-hepatitis C HCC (NBNC-HCC)." (PMID 36250025, 2022).
hepatitis C (3 papers, 2021 to 2024).
liver fibrosis (3 papers, 2019 to 2024). "The possibility that TUG1 accelerates the progression of liver fibrosis by promoting the expression of these pro-fibrotic genes through downregulation of miR-29b is mechanistically argued." (PMID 34899344, 2021). "Collectively, these studies revealed the mechanisms of TUG1 play a crucial role in liver fibrosis, suggesting its ability to monitor human liver fibrosis and its potential to be a candidate biomarker for new therapeutic strategies." (PMID 34899344, 2021). "MEG3 and GAS5 can inhibit liver fibrosis, while TUG1 can protect liver grafts during cold preservation." (PMID 31828106, 2019). "Additionally, some studies have focused on TUG1’s role in energy metabolism and ferroptosis regulation in liver fibrosis." (PMID 39717848, 2024). "TUG1 has also been extensively studied in liver diseases such as cirrhosis and liver fibrosis." (PMID 34899344, 2021).
lung squamous cell carcinoma (3 papers, 2014 to 2024). "Downregulation of TUG1 was also positively related to advanced pathological stage, increased tumor size and decreased survival time in both lung squamous cell carcinoma and adenocarcinoma." (PMID 32117734, 2020). "The study showed that TUG1 could bind to PRC2 at the promoter region of CELF1 and negatively regulate CELF1 expressions in lung squamous cell carcinoma H520 cells." (PMID 38473229, 2024).
neuroblastoma (3 papers, 2019 to 2024). Neuroblastoma (NB) is the most common solid, extracranial childhood tumor. "FMRP has been found to regulate the stability of MDM2 mRNA and the long noncoding RNA TUG1 in mouse neural stem cells and mouse neuroblastoma N2a cells, respectively." (PMID 35534866, 2022). "After 24 h reoxygenation, TUG1 level and microglial M1/M2 phenotype, as well as releasing inflammatory cytokines and their role to viability of SH-SY5Y neuroblastoma cells were determined by quantitative real-time PCR (qRT-PCR), ELISA, immunofluorescence and western blot." (PMID 31551710, 2019).
renal cell carcinoma (3 papers, 2020 to 2021). "lncRNA TUG1 promoted renal cell carcinoma formation via the miR-299-3p/vascular endothelial growth factor (VEGF) axis." (PMID 34039257, 2021). "Taurine upregulated gene 1 (TUG1) and Activated in Renal cell carcinoma with Sunitinib Resistance (ARSR) both modulate the PI3K/Akt pathway to affect chemoresistance." (PMID 33396725, 2020). "lncRNA TUG1 suppressed miR-196A, regulated the MIR-31-5p/flotillin 1 (FLOT1) axis, or regulated yes‐associated protein (YAP) to promote the proliferation and migration of renal cell carcinoma." (PMID 34039257, 2021).
renal fibrosis (3 papers, 2021 to 2022). A final common manifestation of a wide variety of chronic kidney diseases characterized by glomerulosclerosis and tubulointerstitial fibrosis. "Overexpression of the lncRNA TUG1 inhibits cell fibrosis in high glucose-stimulated NRK-52E cells and renal fibrosis in DN mice by targeting the miR-21 and promoting the expression of TIMP3." (PMID 35865316, 2022).
rheumatoid arthritis (3 papers, 2021 to 2023). A chronic, systemic autoimmune disorder characterized by inflammation in the synovial membranes and articular surfaces. "TUG1 level is also significantly upregulated in rheumatoid arthritis, as has been revealed by microarray analysis of lncRNAs in PBMCs and serum exosomes from patients." (PMID 35796900, 2022).
cholangiocarcinoma (2 papers, 2018 to 2020). A carcinoma that arises from the intrahepatic biliary tree (intrahepatic cholangiocarcinoma) or from the junction, or adjacent to the junction, of the right and left hepatic ducts (hilar cholangiocarcinoma). "In patients with cholangiocarcinoma, Kaplan-Meier survival analysis has demonstrated decreased overall survival (OS) and disease-free survival (DFS) in patients with high levels of TUG1 expression." (PMID 33123468, 2020).
chondrosarcoma (2 papers, 2024 to 2025). A malignant cartilaginous matrix-producing mesenchymal neoplasm arising from the bone and soft tissue. "Recent findings indicate that TAMs can be activated by chondrosarcoma‐derived exosomal lncRNA TUG1 (taurine upregulated gene 1), and in turn facilitates the proliferation and metastasis of chondrosarcoma." (PMID 41357670, 2025). "The long non-coding RNA taurine up-regulated gene 1 (TUG1) has been reported to be involved in various cancers, but its role in chondrosarcoma (CHS) remains a mystery." (PMID 40330150, 2024).
chronic kidney disease (2 papers, 2017 to 2020). Impairment of the renal function secondary to chronic kidney damage persisting for three or more months. "However, since Tug1 regulates the transcription coactivator PPARγ coactivator 1α (PGC-1α) expression by epigenetically enhancing PGC-1α promoter activity, it influences chronic kidney disease (CKD) development." (PMID 29050364, 2017).
colon adenocarcinoma (2 papers, 2022 to 2024). "According to the database analysis, the profiles of IGF2BP2 and TUG1 are positively relevant in both Colon adenocarcinoma (COAD) or Rectum adenocarcinoma (READ), which means they may well interact with each other in CRC." (PMID 35014946, 2022).
gastric adenocarcinoma (2 papers, 2022). "The lncRNA TUG1 enhances the malignant behavior of gastric adenocarcinoma by regulating miR-29c-3p to upregulate VEGFA." (PMID 35813862, 2022).
gastric tumor (2 papers, 2018 to 2022). "The RNA-Seq results from the public database TCGA-TANRIC database showed that MALAT1, H19, and TUG1 were among the top twenty overexpressed lncRNAs in gastric tumors." (PMID 29719612, 2018). "Consistent with our results, we also found overexpression of lncRNAs such as H19, GAS5, TUG1, AP5M1 and MALAT1 and downregulation of LINCROR, POU3F3, HOTAIR, FALEC, NBAT1, and ZEB2-AS1 lncRNAs in TCGA gastric tumor datasets." (PMID 29719612, 2018). "Consistent with our data, the lncRNAs H19, GAS5, TUG1, AP5M1, and MALAT1 were found to be overexpressed in TCGA database gastric tumors." (PMID 29719612, 2018).
infantile hemangioma (2 papers, 2021 to 2022). "In infantile hemangioma, miR-137 was found to regulate IGFBP5 expression, and this signaling axis is under the control of the long-noncoding RNA taurine upregulated gene 1 (TUG1)." (PMID 36465383, 2022).
infertile (2 papers, 2024 to 2025). "A novel finding of our study is the observation of downregulated levels of TUG1 in the seminal plasma or sera of both SO and NOA patients compared to infertile men." (PMID 40425698, 2025). "We investigated the seminal plasma and serum expression profiles of TUG1, MALAT1, miR-483, and miR-141 and their targets TGF-β1 and STAT3 in severe male factor infertility." (PMID 40425698, 2025). "TUG1 expression was downregulated in the seminal plasma of both SO and NOA patients compared to controls, with comparable levels in both infertile groups." (PMID 40425698, 2025). "A substantial downregulation of serum TUG1 expression was observed in SO and NOA patients compared to controls, with comparable levels in both infertile groups." (PMID 40425698, 2025). "Additionally, TUG1 knockout resulted in infertility in both male and female rats, consistent with previous studies showing reduced sperm quality in male rats lacking TUG1." (PMID 39595085, 2024). "In this context, this study aimed to investigate the seminal plasma and serum expression of TUG1, MALAT1, miR-483, and miR-141 and their networks TGF-β1 and STAT3 in infertile men with non-obstructive azoospermia (NOA) and severe oligozoospermia (SO)." (PMID 40425698, 2025).
injury (2 papers, 2020 to 2022). Damage inflicted on the body as the direct or indirect result of an external force, with or without disruption of structural continuity. "The lncRNA TUG1 was shown to relieve host inflammatory responses via the miR-494/PDK4 axis and mitigate LPS-induced acute lung injury." (PMID 35495674, 2022).
Insulin resistance (2 papers, 2020 to 2024). Increased resistance towards insulin, that is, diminished effectiveness of insulin in reducing blood glucose levels. "On the other hand, TUG1 down-regulation has been observed in insulin resistance, with a primary effect on islet cell apoptosis." (PMID 32368256, 2020). "In high fat diet-induced GDM mice, TUG1 depletion promoted the expression of miR-328-3p, resulting in the activation of SREBP-2-mediated extracellular signal-regulated kinase (ERK) signaling pathway, causing insulin resistance and apoptosis of pancreatic islet cells." (PMID 40176927, 2024). "Upregulation of TUG1 promoted competitive binding with the target miR-328-3p, normalizing the expression of SREBP-2 and protected the mice from insulin resistance and apoptosis." (PMID 40176927, 2024). "Another important finding of the current study is that SAT mRNA levels of TUG1 were positively correlated with SAT mRNA expression of PGC1α, SREBP-1c, FAS, and ACC independent of age and insulin resistance status." (PMID 32368256, 2020).
kidney injury (2 papers, 2021 to 2022). Trauma to the kidney. "At the same time, upregulating TUG1 presented a protective effect on IRI-induced kidney injury." (PMID 35841017, 2022).
laryngeal carcinoma (2 papers, 2021 to 2023). Carcinoma that arises from the laryngeal epithelium. "lncRNA TUG1 participated in the development of laryngeal carcinoma via inhibiting the activation of RhoA/rho associated coiled‐coil containing protein kinase (ROCK)/matrix metalloproteinase (MMPs) signalling pathway by miR-145-5p." (PMID 34039257, 2021). "Up-regulation of lncRNA TUG1 expression exerts a carcinogenic role by promoting the migration, and invasion of laryngeal cancer cells, and by inhibiting apoptosis." (PMID 34039257, 2021). "Taurine upregulated 1 (TUG1) expression is upregulated in most tumor tissues but downregulated in laryngeal carcinoma and LAD tissues, suggesting that it may have tissue-specific expression patterns and functions in different types of tumors in humans." (PMID 36765563, 2023).
liver disease (2 papers, 2024). "The taurine upregulated gene 1 (TUG1), a 7.1 kb long lncRNA, may modulate ferroptosis via the CYBB-hsa-miR-196a/b-5p-TUG1 axis, thereby affecting the progression of liver disease." (PMID 39717848, 2024).